FCRLB (Fc receptor like B)
Synonyms: FREB-2; FcRY; FCRL2; FCRLM2; FREB2; FLJ31052; FCRLY
Tractability: Antibody: UniProt predicts a signal peptide or a membrane-spanning region.
Gene: Protein-coding gene on chromosome 1 (161,721,544 to 161,728,143, forward strand). Ensembl gene ENSG00000162746.
Subcellular location: Cytoplasm; Endoplasmic reticulum
Subcellular location (Human Protein Atlas): Cytosol
Gene Ontology:
Molecular function: transmembrane signaling receptor activity
Biological process: cell surface receptor signaling pathway; immunoglobulin mediated immune response
Cellular component: cytoplasm; cytosol; external side of plasma membrane; endoplasmic reticulum
Genetic constraint (gnomAD): Loss-of-function variants: 34 observed, 27.87 expected, observed/expected ratio (o/e) 1.22, 90% interval 0.93 to 1.62. The upper end of that interval is the gene's LOEUF score, 1.62, which puts it in group 6 of 6, group 1 being the genes least tolerant of losing a copy. Missense variants: 547 observed, 556.5 expected, observed/expected ratio (o/e) 0.98, 90% interval 0.92 to 1.05. Synonymous variants: 278 observed, 242.16 expected, observed/expected ratio (o/e) 1.15, 90% interval 1.04 to 1.27.
Homologues: Orthologues: chimpanzee FCRLB (99% identical), macaque FCRLB (96% identical), pig FCRLB (89% identical), rabbit FCRLB (88% identical), rat Fcrlb (85% identical), dog FCRLB (85% identical), guinea pig FCRLB (84% identical), mouse Fcrlb (83% identical). Paralogues in human: FCGR1A (29% identical), FCRL3 (28% identical), FCRL4 (27% identical), FCRL5 (26% identical), FCRLA (24% identical), FCER1A (19% identical), FCGR2B (19% identical), FCRL2 (19% identical), FCGR3A (18% identical), FCGR3B (17% identical), FCGR2C (17% identical), FCGR2A (17% identical), and 5 more.
Diseases named in the same sentence as FCRLB in open-access papers:
FCRLB is named in the same sentence as 25 diseases in open-access papers, as found by Europe PMC text mining. Sharing a sentence is not in itself a finding about the gene and the disease. The quoted sentences say what the papers report.
colorectal cancer (1 paper, 2022). A primary or metastatic malignant neoplasm that affects the colon or rectum. "First, the functional roles of FCRLB in regulating tumorigenesis and the development of colorectal cancer were unclear and need to be addressed with further investigation." (PMID 35783274, 2022).
Glioblastoma multiforme (1 paper, 2023). "However, in Adrenocortical carcinoma (ACC) and Glioblastoma multiforme (GBM), the correlations between FCRLB gene expression and Stromalscore, Immunescore, and ESTIMATE score were found to be insignificant." (PMID 37285836, 2023).
lymph node metastasis (1 paper, 2022). "Additionally, we demonstrated that the strong expression of FCRLB was strongly associated with lymph node metastasis and invasion depth, which confirmed, to some extent, the conclusions drawn from our analysis of the TCGA database." (PMID 35783274, 2022).
metastatic melanoma (1 paper, 2023). A melanoma that has spread from its primary site to another anatomic site. "In addition, the expression of FCRLB is higher in malignant and metastatic melanomas compared to melanocytic nevi." (PMID 37285836, 2023).
cancer (2 papers, 2022 to 2023). A tumor composed of atypical neoplastic, often pleomorphic cells that invade other tissues. "The expression of the FCRLB in various cancers has been found to be significantly associated with the markers related to TILs, immunostimulators, and immunoinhibitors." (PMID 37285836, 2023). "While high expression of most FCRL genes is associated with a protective effect in many cancers, FCRLB appears to be a risk factor in several types of cancer." (PMID 37285836, 2023). "On the other hand, FCRLB has been significantly upregulated in colorectal cancer, suggesting its potential as a biomarker for this cancer type." (PMID 37285836, 2023). "In contrast, in other cancers, FCRLB showed a comparatively weaker positive correlation with these markers as compared to other members of the FCRL gene family." (PMID 37285836, 2023). "Our findings revealed that, in the majority of cancer types, all FCRL family genes, with the exception of FCRLB, exhibited a positive correlation with TILs, immunostimulators, and immunoinhibitors." (PMID 37285836, 2023).
tumor (2 papers, 2022 to 2023). "Given the current dearth of studies on FCRLB, further research should elucidate its role in tumor immunity." (PMID 37285836, 2023). "In sum, our study indicated that FCRLB might play an important role in tumor immunity by modulating TME." (PMID 35783274, 2022). "However, the regulatory mechanism of FCRLB in tumor immunity still needs to be further clarified." (PMID 35783274, 2022). "Thus, we speculated that high FCRLB may lead to the formation of an immunosuppressive TME that can promote immune escape and foster tumor growth." (PMID 35783274, 2022). "However, to the best of our knowledge, very few studies regarding the immunological function of FCRLB have been reported previously, and its role in oncology and tumor immunology has never been addressed, partially due to it being a relatively newly defined group within the FCRL family." (PMID 35783274, 2022). "However, the role of FCRLB in modulating TME and tumor immunology has never been addressed before." (PMID 35783274, 2022).
blood cancers (1 paper, 2024). "Among the proteins associated with risk of haematological cancers, we identified associations with risk of multiple blood cancers for members of the FC-receptor protein [FCRL1, FCRL2, FCRL3, FCRL5, FCRLB] and TNF receptor families [TNFRSF4, TNFRSF9, TNFRSF13B, TNFRSF13C, TNFSF13B, TNFSF13]." (PMID 38750076, 2024).
FCRLB also shares sentences with these, for which no sentence is quoted: Autoimmunity (1 paper); breast invasive carcinoma (1); cervical squamous cell carcinoma (1); cholangiocarcinoma (1); esophageal carcinoma (1); glioma (1); head and neck squamous cell carcinoma (1); hepatoma (1); Hypertension (1); IgA Nephropathy (1); infection (1); leukemia (1); lung adenocarcinoma (1); lung squamous cell carcinoma (1); lymphoblastic leukemias (1); lymphoma (1); uterine corpus endometrial carcinoma (1); Virus Infection (1).